PAX6 (paired box 6)
Diseases named in the same sentence as PAX6 in open-access papers (continued):
Sharing a sentence is not in itself a finding about the gene and the disease.
medulloblastoma (7 papers, 2010 to 2025). A malignant, invasive embryonal neoplasm arising from the cerebellum. "GANT61 treatment reduced 40% of the PAX6 expression in canine OSA cells which is in agreement with a previous study wherein GLI1 knockdown reduced the expression of PAX6 in human medulloblastoma." (PMID 24810746, 2014). "It is important to note that medulloblastoma samples showed high expression of PAX6 and it is well known that medulloblastoma is commonly associated with activation/mutation of Hh signaling pathway factors." (PMID 24810746, 2014). "In the course of our studies, we sought to understand the regulation of certain downstream target genes of the Shh pathway, including PTCH1, Cyclin D2, Plakoglobin, NKX2.2, and PAX6, in a panel of medulloblastoma and astrocytoma cell lines and tumors." (PMID 21059263, 2010). "Due to the multifunctional roles of this group of genes, it is entirely possible that other mechanisms regulating PAX6 in medulloblastomas exist, which further need to be explored." (PMID 21059263, 2010). "In this study, we sought to understand the regulatory roles of GLI1, the immediate downstream activator of the Shh signaling pathway on its downstream target genes PTCH1, Cyclin D2, Plakoglobin, NKX2.2 and PAX6 in medulloblastoma and astrocytic tumors." (PMID 21059263, 2010). "In our study, we have silenced expression of GLI1 using a small interfering RNA (siRNA), followed by the determination of gene expression patterns of PTCH1, Cyclin D2, Plakoglobin, NKX2.2 and PAX6 in 14 cell lines and 41 primary medulloblastoma and astrocytoma tumor samples." (PMID 21059263, 2010). "Silencing of GLI1 in Daoy cells indicated that GLI1 may up-regulate the expression of the homeodomain transcription factor I PAX6 in medulloblastomas." (PMID 21059263, 2010). "A few studies report high expression levels of PAX6 in medulloblastoma samples." (PMID 21059263, 2010). "In our study, we monitored the expression of the PAX6 gene in 6 medulloblastoma cell lines and 14 medulloblastoma primary tumor samples: a majority of the cell lines showed moderate expression levels of PAX6 with the exception of the PFSK-1 and D283 cell lines (p = 0.015)." (PMID 21059263, 2010). "These include enhancers of regulators of genes that drive glutamatergic neuronal identity (e.g., PAX6, WLS), and known drivers of medulloblastoma (OTX2, MYCN, CBFA2T2)." (PMID 41279093, 2025). "PAX6 participates neuronal fate determination and can be regulated by SHH signaling in medulloblastoma." (PMID 32508873, 2020). "Interestingly, the fraction of M2 macrophages in Group 4 medulloblastoma were positively correlated with the risk score and were significantly correlated with the expression level of four signature genes (CCNY, SYNE3, CYB5D2, and SELENOV) and four hub genes (GLI2, PAX6, RUNX2, and ZIC1)." (PMID 32508873, 2020). "GLI1 appears to up-regulate PTCH1 expression in both medulloblastomas and astrocytomas, and remaining genes tested, namely, Cyclin D2, Plakoglobin, PAX6, and NKX2.2, only in medulloblastomas." (PMID 21059263, 2010). "Primary medulloblastomas also showed a similar pattern of low expression of NKX2.2 and this correlated with high expression levels of PAX6." (PMID 21059263, 2010). "Statistical analysis by the Fisher's test revealed significant correlations of GLI1 expression with PAX6 (p = 0.015) and NKX2.2 (p = 0.015) expression in medulloblastoma cell lines." (PMID 21059263, 2010). "Additionally, these modules were interconnected via several hub genes, namely, FGFR1, BMP4, PAX6, PAX3, SOX9, and GLI2, all of which have been related to medulloblastomas in previous studies." (PMID 32508873, 2020).
Ataxia (6 papers, 2010 to 2024). Ataxia refers to impaired coordination of voluntary muscle movement. "These Pax6 cKO mice demonstrated a decreased locomotor activity and ataxia due to defects in motor performance and prefrontal deficits, whereas locomotor activity of rSey2/+ rats was normal." (PMID 21203536, 2010).
Glucose intolerance (6 papers, 2017 to 2023). Glucose intolerance (GI) can be defined as dysglycemia that comprises both prediabetes and diabetes. "This patient provides novel evidence that connects PAX6 to glucose homeostasis and highlights that life-threatening hypoglycemia or early onset glucose intolerance may be encountered." (PMID 34200146, 2021).
Hyperglycemia (6 papers, 2014 to 2023). An increased concentration of glucose in the blood. "These phenomena proved that the decreased expression of Pax6 caused by oxidative stress was the main reason for hyperglycemia-induced eye malformation." (PMID 26744353, 2016). "Previous studies revealed that Pax6 loss-of-function in mouse embryonic, as well as adult, pancreas leads to hyperglycemia." (PMID 26658466, 2015). "PAX6 also maintains mature mouse beta cell function and identity; while selective PAX6 deletion in adult mouse beta cells impairs insulin secretion and causes progressive hyperglycemia." (PMID 37933577, 2023). "Pax6 deficiency, achieved by tamoxifen injection, caused progressive hyperglycemia." (PMID 28377501, 2017). "This change was accompanied by significantly decreased plasma insulin levels (1.51 ± 0.15 ng/ml versus 0.83 ± 0.16 ng/ml for Cre−versus Cre+, p < 0.05), suggesting that the observed hyperglycemia, caused by Pax6 deletion, is likely to be due to insufficient insulin output from pancreatic β cells." (PMID 28377501, 2017). "db/db mice with PAX6 replenishment displayed a long‐term improvement in hyperglycemia and elevated serum insulin level with an overall trend up to 5 months compared to db/db mice receiving AAV‐Ctrl." (PMID 37933577, 2023). "Our results show that PAX6 replenishment in diabetic islets not only improves hyperglycemia but also conserves beta cells by enhancing survival and maintaining identity through interactions with other key beta cell transcription factors." (PMID 37933577, 2023). "Genetic deletion of either Pax6 or Gata6 results in hyperglycaemia and decreases the expression of several β-TFs and regulators of GSIS." (PMID 33989778, 2021). "Results showed that the expression of Pax6, Six3 and Otx2 were significantly inhibited by hyperglycemia, but other genes, such as Mitf, Rx1 and Chx10, were not affected significantly (data not shown)." (PMID 26744353, 2016). "In this model, the key genes regulating eye development, Pax6, Six3 and Otx2, were downregulated by hyperglycemia." (PMID 26744353, 2016). "We demonstrated that O-linked N-acetylglucosaminylation (O-GlcNAcylation)-mediated oxidative damage is responsible for the suppression of the Pax6 gene and hyperglycemia-induced eye malformations, which is consistent with the previous results." (PMID 26744353, 2016). "Among these genes, the expression of Pax6 was the most vulnerable to hyperglycemia, being suppressed by 70%." (PMID 26744353, 2016). "Oxidative stress-mediated Pax6 suppression plays a pivotal role in hyperglycemia-induced eye malformation." (PMID 26744353, 2016). "We identified hyperglycemia-mediated suppression of Pax6 as a crucial target for its detrimental effects on chick embryo eye development." (PMID 26744353, 2016). "Moreover, the Pax6 plasmid restored the expression of Six3 and Otx2 to levels that were nearly normal, suggesting that hyperglycemia-induced suppression of Pax6 is the upstream event." (PMID 26744353, 2016). "In our study, overexpression of Pax6 rescued the hyperglycemia-induced eye malformation." (PMID 26744353, 2016). "Similarly, our adult beta-cell-specific Pax6 knockout mice developed hyperglycemia with blood glucose levels reaching as high as 450 mg/dl (see later)." (PMID 26658466, 2015). "As the beta-cell-specific Pax6 KO mice developed a sustained hyperglycemia, we were also interested whether some beta-cell regeneration may have occurred." (PMID 26658466, 2015). "Expression of several β-cell (Pdx-1, MafA, Nkx6.1 and Glut2) and α-cell (Arx, Pax6 and MafB) markers was examined to determine whether the molecular identity of islet cells was altered by exposure to chronic hyperglycaemia." (PMID 25145789, 2014). "Overexpression of Pax6 could effectively rescue hyperglycemia-induced eye malformation." (PMID 26744353, 2016). "However, increased expression of Pax6 in chick embryos could rescue hyperglycemia-induced eye malformation." (PMID 26744353, 2016).
Hyperglycemia (continued). "BG prevented hyperglycemia-induced ROS and MDA formation and significantly restored Pax6 protein expression." (PMID 26744353, 2016). "Thus, we conclude that the alterations in gene expression and function observed in this study are, at least in large part, a reflection of cell-autonomous actions of Pax6 rather than hyperglycemia per se." (PMID 28377501, 2017). "Therefore, it seems that the Nkx6.1 expression may initially be affected by the absence of Pax6 and subsequently also by the developing hyperglycemia in these mice." (PMID 26658466, 2015).
keratitis (6 papers, 2010 to 2025). A corneal disease that is characterized by inflammation of the cornea. "Topical miR-204-5p after LPS-induced keratitis in mice failed to suppress Vegfa, Angpt1, Il-1β, and Tnf-α or rescue Pax6 levels in contrast to in vitro results, although it significantly reduced the inflammatory infiltrate in the cornea." (PMID 39488562, 2024).
melanoma (6 papers, 2012 to 2025). A malignant, usually aggressive tumor composed of atypical, neoplastic melanocytes. "Next, the four parental melanoma cell lines 624, 003, A375, WM-26-4 were transfected with PAX6 siRNA (siPAX6) or control siRNA (siCNT)." (PMID 29855470, 2018). "Moreover, ADAR1 silencing impairs cell invasiveness in melanoma by downregulating β3-integrin at both posttranscriptional and transcriptional levels via paired box 6 (PAX6) and miR-22/miR-30a/d, respectively." (PMID 39126156, 2025). "In melanoma, ADAR1 controls the expression of integrin beta 3 (ITGB3), a cell surface protein associated with tumor invasion, via miR-22 and PAX6 transcription factor at the post-transcriptional and transcriptional levels." (PMID 35898396, 2022). "Until now, there are no data regarding PAX6 role in melanoma progression, however, it has been strongly linked to a feed-forward regulatory loop with MITF during the onset of melanogenesis." (PMID 29855470, 2018). "PAX3 (paired box protein Pax-3) and PAX6 (paired box protein Pax-6) are nuclear transcription factors involved in the development of many tissues and the role of PAX3 in rhabdomyosarcoma and malignant melanoma is discussed." (PMID 23213280, 2012). "Immunostaining revealed the presence of PAX6-negative cells which were positive for vimentin and the melanocyte markers Melan-A and human melanoma black-45 in the basal layer of the limbal epithelium." (PMID 36766742, 2023). "The expression and functional output of both FOXD1, which controls miR-22 expression, and PAX6 are independent of RNA editing, therefore promoting growth and invasion of melanoma." (PMID 35898396, 2022). "To characterize PAX6-negative cells, we performed double immunostaining on corneoscleral tissue sections using epithelial (keratin marker, Pan-CK), stromal (vimentin), and melanocytic (Melan-A and human melanoma black−45 (HMB−45)) markers." (PMID 36766742, 2023).
retinal degeneration (6 papers, 2008 to 2025). Degeneration of the retina. "Conversely, PAX6 expression is higher in c-Fos knockout mice, which manifest resistance to light-induced retinal degeneration." (PMID 34298993, 2021). "Another research group has shown that in rd1 mice (a common model of inherited retinal degeneration), the decrease in the PAX6 protein expression is accompanied by a peak of photoreceptor apoptosis (between P10 and P14)." (PMID 34298993, 2021). "In this study, we found that at the early stages of retinal degeneration, Müller cells expressed the proliferative marker BrdU, stem/progenitor markers PAX6 and SOX2." (PMID 27384999, 2016). "Pax6 overexpression does not obviously impair the initial formation of the eye and its major cell-types but prevents normal development of the retina from about E14.5, leading eventually to severe retinal degeneration in postnatal life." (PMID 18507827, 2008).
corneal diseases (5 papers, 2012 to 2023). "With this method, we identified that the genes associated to our “curated corneal disease list” were significantly more likely to be bound by PAX6, FOXC1, RUNX1, and FOSL2." (PMID 37856539, 2023). "Previous studies have shown that the knockdown of miR-184 results in a decrease in Pax6, and its deregulation has been associated with corneal diseases." (PMID 36289615, 2022). "Therefore, PAX6, as a key factor in corneal endothelial wound healing and SUMOylation-deficient PAX6 protein with higher stability can be potentially applied as therapeutic methods to treat or prevent corneal diseases, and not only endothelial injuries." (PMID 32826860, 2020). "To further explore the association of FOSL2 with corneal diseases, we questioned whether the target genes of FOSL2 are enriched for corneal disease genes, similar to other known LSC TFs such as PAX6, FOXC1, and p63." (PMID 37856539, 2023). "Topical application of Shh has already been reported to improve corneal epithelial wound healing in wild-types, but its effect on Pax6 mutants has not been investigated, in spite of its therapeutic potential for corneal disease." (PMID 22275805, 2012).
embryonal carcinoma (5 papers, 2013 to 2025). A non-seminomatous malignant germ cell tumor characterized by the presence of large germ cells with abundant cytoplasm resembling epithelial cells, geographic necrosis, high mitotic activity, and pseudoglandular and pseudopapillary structures formation. "Mouse embryonic carcinoma P19 cells, which are frequently used for the functional analysis of the Pax6 gene, were transfected with mouse Shh cDNA encoding the N-terminal half of the product (Shh-N)." (PMID 39859210, 2025). "To address the possibility that Dmrta2 affects Pax6 E60 enhancer activity and investigate its mechanism of action, we performed transfection experiments in P19 mouse pluripotent embryonal carcinoma cells that have neurogenic potential." (PMID 40541527, 2025). "In the current study, the epigenetic role of nuclear actin ontranscription regulation of two stemness (OCT4 and NANOG)and two differentiation) NESTIN and PAX6) marker genes was evaluated in a human embryonal carcinoma cell line (NT2)before and after differentiation induction." (PMID 27540526, 2016). "To further test whether Gaa, Isl1, Kif1b, Mtmr2, Pcsk1n, and Snca, are regulated by Pax6, we performed co-transfection studies in cultured P19 embryonic carcinoma and αTN4-1 lens epithelial cells." (PMID 23342162, 2013). "After treatment with ATRA, known to induce differentiation of embryonal carcinoma NT2 cells, LIN28 expression was significantly downregulated, as it happened with pluripotency factors NANOG and POU5F1, with the opposite occurring for PAX6, a marker of differentiation." (PMID 40448114, 2025).
gastric cancer (5 papers, 2015 to 2022). A primary or metastatic malignant neoplasm involving the stomach. "miR-488 was reported to function as a tumor suppressor in human prostate and gastric cancer by targeting androgen receptor and PAX6." (PMID 29113360, 2017). "miR-488 is downregulated in gastric cancers and functions as a tumor suppressor by targeting PAX6 expression." (PMID 29113360, 2017). "PAX6 can promote palbociclib in gastric cancer via suppressing Hippo signaling." (PMID 34459131, 2021). "Induction of the Hippo signaling pathway or treatment with DNA methylation inhibitor could overcome PAX6‐induced palbociclib resistance in gastric cancer." (PMID 34459131, 2021).
iris coloboma (5 papers, 2007 to 2024). "Approximately 80% of congenital iris coloboma cases are caused by the gene mutation of human paired box-6 (PAX6)." (PMID 32148946, 2020). "Partial penetrance of another PAX6 homeodomain mutation (R242T) was also observed in the case of a child with unilateral iris coloboma, whose mutation carrier mother was completely unaffected." (PMID 17397257, 2007).
ptosis (5 papers, 2012 to 2017). The drooping of the upper eyelid. "Two case reports individually mentioned that mutated Pax6 results in reduced vision, photophobia and eyelid ptosis in an autistic child patient, and is responsible for impaired auditory sensory and higher order interhemispheric transfer in a 12 year old child." (PMID 25051057, 2014). "Although PAX6 mutations may cause the phenotype of congenital ptosis, comparing the feature of ptosis with his mother, we didn’t find his bilateral ptosis was more serious than his mother’s, which suggested that his bilateral ptosis with ophthalmoplegia was caused by the KIF21A mutation." (PMID 23799907, 2013).
Retinal dysplasia (5 papers, 2006 to 2020). Abnormal growth and differentiation, structure and appearance of the retina present from birth. "Before the onset of severe retinal dysplasia, Pax6 overexpression causes defects of retinal axons, preventing their normal growth and navigation through the optic chiasm." (PMID 18507827, 2008). "No retinal dysplasia was observed in any of the Pax6+/- eyes studied (n = 14)." (PMID 17029624, 2006).
Alzheimer disease (4 papers, 2017 to 2023). A progressive, neurodegenerative disease characterized by loss of function and death of nerve cells in several areas of the brain leading to loss of cognitive function such as memory and language. "Pax6 is an important transcription factor for eye, brain and olfactory system development, some researchers found that there are probably more targets and downstream pathways of Pax6 involved in Alzheimer’s disease pathogenesis." (PMID 35573291, 2022). "We found that environmental enrichment greatly affects the expression of markers specific for stem cells, progenitor cells and differentiated neurons (Pax6, Ngn2, NeuroD1, NeuN) in the hippocampus of young adult rats or rats with Alzheimer’s disease (AD) model but less efficiently in aged animals." (PMID 28798684, 2017). "The female-biased genes in four regions were enriched for Alzheimer’s disease progression (SYN3 and STK32B) and the male-biased genes in four brain regions were enriched for neuroticism (PAX6 and PLTP)." (PMID 37221602, 2023). "And Pax6 expression is increased in the brains of APP transgenic mice and human Alzheimer’s disease patients." (PMID 35573291, 2022).
aphakia (4 papers, 2009 to 2024). "We found that transcription factors implicated in vertebrate lens development (Prox1a, MafB, c-Maf, FoxE3) failed to initiate expression in the presumptive lens tissue of Pax6.1 mutant fish resulting in aphakia, a phenotype observed previously in Pax6 mutant mice." (PMID 39512904, 2024).
autosomal dominant congenital cataracts (4 papers, 2011 to 2022). "The mutation as either G78V or G64V based on the splice variant identified in the current study is in the paired domain of PAX6 and causes autosomal-dominant congenital cataracts with microcornea in the kindred C343." (PMID 33339270, 2020). "Overall, we report four novel mutations in HSF4, CRYGA, CRYGC and PAX6, and one previously reported mutation in GJA3 that cause autosomal dominant congenital cataracts." (PMID 36670602, 2022).
Blindness (4 papers, 2015 to 2023). Blindness is the condition of lacking visual perception defined as a profound reduction in visual perception. "The results of our study indicate that alternation of Pax6 function may cause the activation of apoptosis and further contribute the blindness in vestimentiferan tubeworms." (PMID 28005979, 2016).